MMP2 (matrix metallopeptidase 2)
Diseases named in the same sentence as MMP2 in open-access papers (continued):
Sharing a sentence is not in itself a finding about the gene and the disease.
glioma (continued). "BmKCTa, the most common CTX-like peptide investigated, also demonstrated the inhibition of glioma cell proliferation, migration, and invasion in a fashion similar to CTX with MMP-2 as the potential target." (PMID 37444498, 2023). "We further performed Western blot analysis to examine the expressions of SCIN, MMP2, and MMP9 in 37 fresh frozen glioma samples and 6 normal tissues." (PMID 36291348, 2022). "High expression of MMP2 and MMP9 has been described in glioma, correlated with tumor grade and localized to the cytoplasm of tumor cells, endothelial cells, and their extracellular matrix." (PMID 34980260, 2022). "The expressions of MMPs, including MMP-2 and MMP-9, have been shown to coordinate calcium mobilization and induce glioma cell metastasis." (PMID 35012441, 2022). "The AgPNPs were conjugated with chlorotoxin, a 36-AA scorpion toxin that binds the matrix metalloproteinase 2 (MMP2) of glioma cells, and was sequestered in a flank glioma in mice after IV administration." (PMID 35745855, 2022). "Mesenchymal markers, including N-cadherin, slug, snail and metastasis-related genes including MMP2, MMP9 and TIMP3 were widely investigated and verified in glioma remedy mechanisms." (PMID 36234681, 2022). "In vitro studies indicate that BV has both cytotoxic and inhibitory effects on the secretion of MMP-2 and MMP-9 in selected lines of glioma, suggesting anticancer properties of BV." (PMID 35221898, 2022). "MMP-2 and MMP-9 protein expression can be significantly upregulated upon miR-221/222 overexpression and promote proliferation and invasion of glioma cells in the presence of the Akt downstream pathway." (PMID 36479040, 2022). "The GL261 glioma cell line and activation of TLR2 upregulated the expression of MMP2 and MMP9 to promote tumor invasion, indicating that TLR2 signaling in glioblastoma stem cells (GSCs) is involved in the invasiveness of glioma." (PMID 36611945, 2022). "Meanwhile, matrix metalloproteinases [MMP2, MMP9, and membrane-type matrix metalloproteinase 1 (MT1-MMP)] were also detected in glioma tissues of grades IV and III." (PMID 35098869, 2022). "In the presence of glioma cells, microglia produce significant amounts of TGF-β, which in turn induces production of matrix metalloproteinase 9 (MMP9) and MMP2, leading to degradation of ECM and supporting glioma stem cell invasion." (PMID 36776369, 2022). "TGF-β signaling, subsequently activates a plethora of signal transduction pathways shown to trigger, among others, MMP2 and MMP9 expression by glioma cells thereby promoting invasiveness." (PMID 35992852, 2022). "We show that UII treatment of GBM xenografts evoked MMP-2 and MMP-9 overexpression mainly in the vascular and glioma cell compartments, respectively, and that UII stimulates MMP9 gene expression in hCMEC/D3 in vitro." (PMID 33937253, 2021). "Another study found that overexpressing MAGI1 inhibits proliferation, migration, and invasion of glioma cells by regulating cell growth and EMT through AKT, matrix metalloproteinase 2 (MMP2) and MMP9, and the E-cadherin/N-cadherin/vimentin pathway." (PMID 34198584, 2021). "MiR‐129‐5p overexpression obviously reduced the MMP‐2 and MMP‐9 protein levels and the luciferase activities of NF‐κB, indicating that miR‐129‐5p blocked the NF‐κB pathways to suppress glioma angiogenesis and growth." (PMID 33300633, 2021). "The transcription factor SP2 directly bound to the promoter regions of the VM formation-related proteins MMP2, MMP9, and VE-cadherin, playing a role in promoting transcription in order to regulate the VM formation ability of glioma cells." (PMID 33542193, 2021). "The expression of both MMP2 and MMP14 are significantly increased in grade IV GBMs in comparison with lower grade gliomas." (PMID 33919029, 2021). "It is indicated that SP2 can regulate the expression of MMP2, MMP9, and VE-cadherin and promote the formation of VM in glioma cells at the transcriptional level." (PMID 33542193, 2021).
glioma (continued). "MMP-2 and MMP-9 have a synergistic effect on endothelial basement membrane degradation in gliomas and mediate the release of ECM-sequestered VEGF." (PMID 34200145, 2021). "Thus, by regulating the MMP2-related pathway, glioma angiogenesis could be inhibited." (PMID 33889541, 2021). "A study on ANG-2 in human gliomas found overexpression of ANG-2 in the invasive areas of the brain, accompanied by matrix metalloprotease-2 (MMP-2) and increased angiogenesis." (PMID 34439141, 2021). "Initially, we explored the mRNA expression of MMP2, MMP9 and MMP14 in the human glioma cell lines T98G, U87MG, U138MG, U251MG and A172 by real time RT-qPCR." (PMID 33919029, 2021). "Immunoblotting analysis showed that after 48 h of treatment with PTE, the expression levels of MMP-2 and MMP-9 proteins in glioma cells were significantly reduced and dose-dependent." (PMID 33737656, 2021). "Microglia have been demonstrated to upregulate matrix-altering enzymes, especially MMP-2 and MMP-9, to facilitate glioma infiltration." (PMID 32172480, 2021). "MMP-2 and/or MMP-9 are upregulated by microglia in disorders where PNN breakdown occurs, such as stroke, multiple sclerosis, and glioma, and pharmacological MMP blockade in glioma ameliorates enhanced MMP-2/9 activity and associated PNN loss." (PMID 34413489, 2021). "And some researchers found that the mechanism of MMP14 in glioma mainly works by cutting CD44, or via the combination of TIMP-2 and MMP14 to activate MMP-2 and MMP9 to enhance tumor invasion and tumor cell proliferation." (PMID 34712139, 2021). "In conclusion, these data suggest that curcumin effectively alleviated the invasion of glioma promoted by adverse psychological stress through inhibiting the MAPK/ERK signalling pathway which reduced the expression of CD147 and MMP‐2/9." (PMID 34169637, 2021). "As reported in the literature, MMP2 and MMP9 are closely related to vasculogenic mimicry formation in gliomas." (PMID 33889541, 2021). "The results revealed that knockdown of TROAP drastically downregulated the level of MMP2, MMP7, MMP9, RHOA, RHOA, ROCK1 protein in U251 glioma cell lines compared to control group (p < 0.05)." (PMID 34077623, 2021). "Factors released by both TAMs and tumor cells induce the reciprocal expression of MMP2, MMP9, and MT1-MMP, that degrade the ECM facilitating glioma migration." (PMID 34690699, 2021). "Our study found that HNRNPD was highly expressed in glioma tissues and cells, knockdown of HNRNPD significantly reduced the expression of MMP2, MMP9, and VE-cadherin in U87 and U251 cells, further inhibited the VM formation." (PMID 33542193, 2021). "We also performed ELISA detection and found that BATF2 upregulation significantly decreased VEGFA, MMP2, and MMP-9 levels in glioma tissues (VEGFA: p < 0.001; MMP2: p < 0.01; MMP-9: p < 0.01) and exhibited decreased MMP-9 staining in U251-BATF2 tumour." (PMID 33452462, 2021). "Matrix Metalloproteinase 2 (MMP2), which is involved in regulating the extracellular matrix, plays significant roles in glioma migration and invasion." (PMID 33336871, 2021). "Second, TTF application decreases the levels of VEGF, HIF1α, MMP‐2 and MMP‐9 via the suppression of NF‐κB, thus suppressing glioma angiogenesis." (PMID 33300633, 2021). "Pam3CSK4 increased the migratory and invasive capability of GSCs by enhancing MMP-2 and MMP-9 expression, while TLR2 knockout attenuated the effects and prolonged survival in glioma mouse model." (PMID 34715891, 2021). "MDSCs release vascular endothelial growth factor A (VEGFA) and matrix metalloproteinases (MMP2 and MMP-9) to promote glioma growth." (PMID 33452462, 2021). "Knockdown of SP2 significantly inhibited the mRNA and protein expression level of MMP2, MMP9, and VE-cadherin, thereby repressed the VM formation ability of glioma cells." (PMID 33542193, 2021).
glioma (continued). "Fibulin-3 also drives glioma invasiveness, a process mechanistically underpinned by modulation of the ECM surrounding the tumour through increasing expression of MMP2, MMP9, and ADAMTS-5." (PMID 32911658, 2020). "Our results revealed that MMP-2 and MMP-9 expression in glioma cells were increased at both the RNA and protein levels after NE treatment, whereas CD147 silencing inhibited MMP-2 and MMP-9 expression (P<0.05)." (PMID 33178600, 2020). "Indeed, Ang2 interacted with α5β1 integrin in Tie2- deficient human glioma cells, leading to activation of focal adhesion kinase (FAK), p130Cas, extracellular signal-regulated protein kinase (ERK) 1/2, and c-jun NH2-terminal kinase (JNK) and induction of MMP-2 expression and secretion." (PMID 32085414, 2020). "Mechanistically, KLHDC8A regulated various functions in glioma by directly mediating Bcl2, BAX, p21, CDK2, MMP2 transcription and ERK and P38 MAPK activation." (PMID 32851798, 2020). "The expression of VE-cadherin, MMP-2, and MMP-9 was inhibited after HOXA-AS2 knockdown, according to the study, miR-373 was downregulated in glioma samples, but the expression of miR-373 was upregulated after HOXA-AS2 knockdown." (PMID 32169087, 2020). "Survival analysis showed that the expressions of S100A4, FN1, and MMP-2 were negatively correlated to over-survival significantly in GBM and Brain Lower Grade Glioma." (PMID 33004792, 2020). "The relationship between the presence of miRNA and the activity of metalloproteinases (MMP2, MMP3, MMP9, MMP12, MMP13, ADAM9) was demonstrated in many other observations conducted on gliomas, including glioblastoma." (PMID 32349263, 2020). "LncRNA HOXA-AS2 promotes vasculogenic mimicry in glioma cells by binding to miR-373 and increasing the expression of EGFR and its downstream effectors VE-cadherin, MMP2, and MMP9." (PMID 32993787, 2020). "In addition, correlation analysis indicates that SLC39A1 is highly correlated with MMP2\MMP9, suggesting that the up-regulated expression of SLC39A1 may promote the progression of glioma by increasing the intake of zinc ions and increasing the expression level of MMP2\MMP9." (PMID 33292262, 2020). "SH3GL2, as a suppressor for tumors, and has reduced expression in glioma tissues promoting migration and infiltration of glioma cells by enhancing STAT3/MMP2 signaling." (PMID 32328342, 2020). "Transfection of RIOK2 siRNAs significantly inhibited glioma cell migration and invasion and down‐regulated the expression of MMPs (MMP2 and MMP9) and mesenchymal markers (N‐cadherin, β‐catenin, Twist1, fibronectin, ZEB‐1) in glioma cells." (PMID 32125767, 2020). "In glioma cells, cell invasion was inhibited by BMAL1 overexpression through blocking of PI3K/AKT/matrix metalloproteinase-2 (MMP2) pathway where BMAL1 attenuates BCL-W oncogene that activates the invasion pathway." (PMID 32195174, 2020). "Another study showed that HIF induces TGF-β2, leading to the upregulation of MMP-2 and MMP-9 expression in human glioma cells." (PMID 32867190, 2020). "GAM-derived TGF-β2 and β1 have been shown to increase matrix metalloproteinase 2 (MMP-2) expression, thereby promoting ECM deposition and promoting glioma invasion." (PMID 33511267, 2020). "The role of some of them (MMP-2, MMP-9, MMP-14) has been proved in the process of developing high grade gliomas." (PMID 32349263, 2020). "Matrix metalloproteinases, such as MMP-2 and MMP-9, are related to the tumor grade and the invasive capacity of glioma." (PMID 31467533, 2019). "MMP-2 and MMP-9 have been described to play an important role in the migration, invasion, and metastasis of glioma cells." (PMID 31551765, 2019). "For example, when exposed to glioma cells, GAMs upregulate expression of membrane type 1–matrix metalloproteinase (MT1-MMP) that cleaves pro-MMP2 to facilitate degradation of the extracellular matrix and GBM invasion." (PMID 31467533, 2019).
glioma (continued). "It has been shown that the activity of certain matrix metalloproteases, such as MMP-2 (gelatinase A), MMP-9 (gelatinase B), MMP-14 (matrix metalloproteinase 14) is related to the pathophysiology of high-grade gliomas." (PMID 31661771, 2019). "PIWIL1 also regulates apoptosis and cell cycle progression through P21, Cyclin D1, BCL-2 and BAX, and migration through expression of MMP-2 and MMP-9 in glioma cells." (PMID 31443431, 2019). "To determine this, we used the transcriptional reporters MMP1-lacZ and MMP2-lacZ in control and glioma, and the results show only a few cells with MMP1 and MMP2 transcriptional reporters activated in glial cells (arrowheads) in both control and glioma brains." (PMID 31846454, 2019). "The anti-tumor activity of miR-149 in glioma cells was found to be correlated with low-expression of PCNA, p-AKT1, cyclin D1, and MMP-2." (PMID 31297133, 2019). "Results showed that expression level of E-cadherin and Claudin was increased, and that of N-cadherin, PLOD2, MMP2 and Snail was significantly decreased after SKA1 knockdown in glioma cells." (PMID 31827398, 2019). "Previous research has shown that matrix metalloprotease-2 (MMP-2) and MMP-9 expression are significantly elevated in high-grade gliomas." (PMID 30551687, 2018). "Invasive gliomas show MMP2 and MMP9 overexpression and both MMP2 and MMP9 play important roles in infiltrative growth of gliomas." (PMID 30587839, 2018). "ANO1 is also involved in cell migration and invasion by regulating the expression of MMP2 and MMP9 in glioma cells." (PMID 29416639, 2018). "In U87 glioma cells, irradiation increased the β-catenin/TCF transcriptional activity, followed by an upregulation of its downstream genes, MMP2, and MMP9." (PMID 30134800, 2018). "FOXM1 was shown to stimulate angiogenesis in several cancers, including pancreatic cancer, gastric cancer and glioma, through induction of vascular endothelial growth factor (VEGF), matrix metalloproteinase-2 (MMP-2) and MMP-9." (PMID 30486864, 2018). "In particular, GAM-derived TGF-β2 induces the expression of MMP-2, an enzyme which promotes ECM deposition and thus facilitates the invasive properties of glioma cells in vitro." (PMID 29389898, 2018). "Both siPLP2 transfected gliomas showed a clear inhibition of glioma cell proliferation, migration, and invasion as well as down-regulating p-p38, p-ERK, MMP-2, and MMP-9 expression." (PMID 30373180, 2018). "As an example, in glioma, the downregulation of miR-383 stimulates AKT signaling and controls the expression of Matrix Metalloproteinase II (MMP2), through the regulation of IGF-1R, thereby controlling tumor cells invasiveness." (PMID 30469501, 2018). "Many studies have shown that MMP-2 and TIMP-2 play crucial roles in various human cancers, including gliomas." (PMID 26729052, 2017). "The obtained results proved that knocking down of SH3GL2 markedly aggravated the migration and invasion of glioma cells by activating the STAT3 signalling thereby promoting the expression and secretion of MMP2." (PMID 28470949, 2017). "Meanwhile, the Foxm1 gene downstream of GLI1, via targeting CyclinD1 and MMP-2 and regulating TGF-β1 signaling, is critical in promoting EMT of glioma cells." (PMID 28446712, 2017). "So far, the prognostic value of matrix metalloproteinase 2 (MMP-2) and tissue inhibitor of matrix metalloproteinase 2 (TIMP-2) expressions in patients with gliomas has been widely reported, especially in China." (PMID 26729052, 2017). "In order to evaluate the essential roles and clinical utilities of MMP-2 and TIMP-2 in gliomas, we performed a meta-analysis." (PMID 26729052, 2017). "In conclusion, overall data demonstrated the tumor-suppressive role of MALAT1 in glioma by attenuating ERK/MAPK-mediated growth and MMP2-mediated invasiveness." (PMID 26938295, 2016).
glioma (continued). "The induction of MMP-2 and/or MMP-9 by Bcl-2 overexpression is mediated by AP-1 in lung cancer cells, furin and TGF-β in glioma cells, and the N-cadherin/FGF receptor/ERK pathway in squamous carcinoma cells." (PMID 26621844, 2016). "Specifically, MMP-2 and MMP-9 are activated during angiogenesis and glioma invasion, and both of these enzymes can be measured in the CSF." (PMID 27876012, 2016). "Specifically, knockdown of Bax and Bak in glioma, colon, or lung cancer cells promotes cell invasion by stimulating the PI3K/Akt/MMP-2 pathway, and Bax-knockout MEFs are consistently more invasive than control MEFs." (PMID 26621844, 2016). "There is a strong correlation between elevated MMP levels, such as MMP-2 and MMP-9 and tumor cell invasiveness in glioma." (PMID 26305187, 2015). "The matrix metalloprotease MMP-2 is involved in ECM degradation, and the local enzymatic activity of this protein in the tumor environment should logically favor glioma cell division and migration." (PMID 25826056, 2015). "In a glioma cell line, gene silencing of HIF-1α can downregulate MMP-2/MMP-9 to suppress cell migration and invasion into adjacent normal tissue." (PMID 25816356, 2015). "Up-regulation of miR-335 in glioma cells reduces expression of PAX6, thus promoting cell proliferation and is accompanied by increased protein levels of MMP-2 and MMP-9." (PMID 26204513, 2015). "An imbalance between MMP-2 and TIMP-2 has an important role in glioma invasion by degradation of the ECM." (PMID 26245666, 2015). "In the glioma tissues of grade II, III and IV, the relative mRNA expression of MMP2 was 4.36±0.63, 6.53±0.75 and 8.26±0.59, respectively, significanlty higher compared to the normal brain tissues (all P<0.05)." (PMID 25872784, 2015). "MMP-2 and MMP-9 are overexpressed in experimental glioma models and patient tissue samples and play an important role in glioma progression, particularly in tumor invasion." (PMID 26663949, 2015). "Previously, leptin was reported to be able to increase the expression of MMP-2, MMP-7 or MMP-9 in different cancer cells, as well as the expression of MMP-13 in glioma cells." (PMID 25948792, 2015). "Elevated levels of MMP-2, MMP-9, MMP-9/NGAL, and some high molecular weight MMPs have been found in the urine, cerebrospinal fluid, and tumor tissue specimens from glioma patients." (PMID 26663949, 2015). "Both MMP-2 and MMP-9 have independently been found to be down-regulated after treatment with pioglitazone, suggesting the role of PPARγ agonists in reducing glioma cell invasiveness." (PMID 24672773, 2014). "Our results demonstrate that MMP-2-depleted-CM abrogated IR-induced SDF-1/CXCR4 expression and PI3/AKT-mediated angiogenesis in glioma xenograft cells." (PMID 23381805, 2013). "We also showed that artemether significantly promoted the apoptosis of U87 cells and inhibited the expressions of MMP-2 and MMP-9, which are the two major proteolylic enzymes involved in the invasion and metastasis of gliomas." (PMID 23593320, 2013). "MMP-2 and MMP-9 contribute most in the malignancy of gliomas among other MMPs and are highly expressed in glioma tissues." (PMID 23593320, 2013). "Inhibition of PHGDH expression in glioma cells downregulated the expression of VEGF, MMP-2, CHK2 and cyclin D1 and reduced glioma cell proliferation, invasion and tumorigenicity in vitro and in vivo." (PMID 23229761, 2013). "In vitro study revealed that blocking of MMP-2 and MMP-9 resulted in inhibition of human malignant glioma cell invasion, indicating that MMP-2 and MMP-9 play an important role in the metastasis and invasion of glioma cells." (PMID 23593320, 2013). "Here, we show that the constitutive MMP-2 expression and activity were higher than that of MMP-9 for both glioma cell lines." (PMID 23533307, 2013).